REN (renin)
Diseases named in the same sentence as REN in open-access papers (continued):
Sharing a sentence is not in itself a finding about the gene and the disease.
COVID-19 (continued). "Meanwhile, a preliminary report from Wuhan and a more extensive retrospective cohort described that ANGII levels in COVID-19 were markedly elevated and closely associated with lung injury, while renin levels remained similar to controls." (PMID 33893295, 2021). "Recently a meta-analysis showed an association between Renin–Angiotensin–Aldosterone System inhibitors and clinical outcomes in patients with COVID-19." (PMID 34225749, 2021). "Vitamin D deficiency also increases the activity of the X-chromosome-linked “Renin-Angiotensin” System, making vitamin D deficient individuals (especially men) more susceptible to COVID-19's deadly “cytokine storm” (dramatic immune system overreaction)." (PMID 33014983, 2020). "Furthermore, dysregulation in the Renin–Angiotensin System (RAS) was linked to the systemic manifestations of COVID-19, which has key roles in the regulation of vascular tone, electrolyte balance, inflammation, thrombosis and response to injury." (PMID 38195459, 2024). "One is that long-term COVID-19 may cause direct renal damage by infiltrating inflammatory cells or through the overactivation of the renin-angiotensin-aldosterone (RAAS) system, which is thought to enhance kidney damage over time." (PMID 38287815, 2024). "9B KEGG pathways were significantly associated with sarcopenia and COVID-19 common hub genes: chemical oncogenic-receptor activation of tryptophan metabolism, Chagas disease, cellular senescence, One carbon pool by folate, and renin-angiotensin system." (PMID 38978778, 2024). "The underlying causes of POTS following COVID-19 remain unknown, with various theories proposed such as renin–angiotensin–aldosterone system (RAAS) dysregulation, hyperadrenergic reaction, and direct viral infection." (PMID 39202605, 2024). "Systematic reviews and meta-analyses as well as Mendelian randomisation analyses among the general population also indicated a lower risk of severe COVID-19 with chronic use of statins and renin inhibitors, supporting our findings from meta-analyses adjusted for important confounders." (PMID 37204441, 2023). "It is plausible that this may be due to the downregulation of the renin-angiotensin-aldosterone system, or endothelial damage and thrombo-inflammation caused by COVID-19." (PMID 35815299, 2022). "In addition, being physically active prevents and treats numerous complications associated with COVID-19, such as heart disease, and neurological and metabolic disorders, including the positive effect on the renin–angiotensin system." (PMID 36429628, 2022). "Future research should focus on biomarkers of tubule damage predicting AKI and whether modulation of ACE2 expression by renin-angiotensin system inhibitors may be beneficial for COVID-19 patients, diminishing the risk of AKI." (PMID 35928822, 2022). "ACE-2 receptor has a vital function in the pathogenesis of COVID-19, activating the coagulation system (causing thrombophilia), the renin-angiotensin system (leading to cardiovascular instability) and the kinine–kallikrein system (causing acute inflammatory lung oedema)." (PMID 34399734, 2021). "A role of over activation of the renin–angiotensin–aldosterone system (RAAS) has been implicated in worsening of the status of hospitalized COVID-19 patients based on observed higher MBP and lower serum potassium as markers of RAAS activation in patients with deteriorating respiratory function." (PMID 34642385, 2021). "Both entry from the luminal and basolateral sides of the renal tubular cells are the possible routes for COVID-19, and the microthrombi associated with severe sepsis and the dysregulated renin–angiotensin–aldosterone system worsen further renal injury in SARS-CoV-2-associated AKI." (PMID 33153216, 2020). "Moreover, the level of angiotensin II in COVID-19 patients was strongly associated with viral load and lung injury, suggesting that COVID-19 was causing an imbalance in the renin–angiotensin system." (PMID 32403242, 2020).
COVID-19 (continued). "There is certainly emerging and existing evidence to postulate a mechanism through which this vitamin might play an essential role in the fight against COVID-19, including its association with the pulmonary renin-angiotensin system." (PMID 32842513, 2020). "On the one hand, SARS-CoV-2 infection can cause an inflammation status leading to vitamin D deficiency, while, on the other hand, lower serum vitamin D levels may contribute to a dysregulation of the renin–angiotensin system and thus may increase the risk of developing a cytokine storm in COVID-19." (PMID 38732592, 2024). "Therefore, they hypothesized that dysfunction of the renin-angiotensin system and inflammatory response are common pathogenic molecular pathways in patients with COVID-19 and OA." (PMID 37283761, 2023). "The 25(OH) vitamin D levels may be linked to COVID-19 outcomes through several mechanisms, including innate and adaptive cellular immunity, and renin–angiotensin system regulation; therefore, this suggests that increasing 25(OH) vitamin D concentration may improve the prognosis of COVID-19." (PMID 38004213, 2023). "The involvement of the renin–angiotensin system (RAS) in the pathophysiology of coronavirus disease 2019 (COVID-19) is commonly discussed, because angiotensin-converting enzyme 2 (ACE2) is a functional receptor of SARS-CoV-2, and at the same time, a counter-balance for ACE in the RAS." (PMID 35458690, 2022). "The same case could apply to the simultaneous use of metformin and A.C.E. inhibitors, as evidence suggested that the use of metformin, another antidiabetic drug, and renin-angiotensin system inhibitor were associated with lower severity and mortality in COVID-19 patients." (PMID 36289885, 2022). "Additionally, vitamin D deficiency may potentially affect susceptibility to COVID-19 through its role in activating the pulmonary renin angiotensin system and regulating ACE2 which plays a role in lung injury protection." (PMID 34314458, 2021). "Demographic and clinical comorbidities associated with the severity of infection suggest that possible variants known to influence the renin–angiotensin–aldosterone (RAAS) pathway (those that influence ACE2) may contribute to the heterogenous infection response to COVID-19." (PMID 32501190, 2020). "Severe acute respiratory syndrome Coronavirus 2 (SARS-CoV-2) enters host cells by binding to angiotensin-converting enzyme 2 (ACE2), implicating dysregulation of the renin-angiotensin system (RAS) in COVID-19 pathophysiology." (PMID 42043254, 2026). "COVID-19 perturbs the renin-angiotensin system (RAAS) and inflammatory pathways, shaping disease severity." (PMID 42074217, 2026). "The resulting network revealed several highly connected hub proteins, including IL1B, IL6, TNF, ACE, and REN, which are central regulators of inflammatory and cardiovascular pathways known to play key roles in COVID-19 pathogenesis." (PMID 41471341, 2025). "Among the 19 intersecting targets identified between G. pentaphyllum compounds and COVID-19-associated genes, several key nodes—IL1B, IL6, TNF, ACE, and REN—emerged as central in both the protein–protein interaction and compound–target networks." (PMID 41471341, 2025). "The impact of the ACE2 rs2074192 gene polymorphism on cytokine production (IL-1β, IL-6, IL-8, and TNF-α) is also significant and should be considered when implementing renin-angiotensin-aldosterone system targeting drugs in COVID-19 therapy." (PMID 40066463, 2025). "ACE2, a critical regulator of the renin–angiotensin system, plays a significant role in COVID-19 pathogenesis." (PMID 40868984, 2025). "Orexin A regulates sleep–wake cycles, arousal, and energy homeostasis, linking it to the renin–angiotensin system and substance P. Dysfunction in these pathways occurs in acute and long-term COVID-19, including post-COVID syndrome." (PMID 40529720, 2025).
COVID-19 (continued). "The results reinforce the key role that the angiotensin-converting enzyme 2 has on COVID-19 pathophysiology as a point of convergence between the renin–angiotensin and kallikrein–kinin systems." (PMID 40559541, 2025). "Generally, individuals with COVID-19 more commonly have a long-term clinical history of kidney or heart disorders, which is supported by a disordered renin-angiotensin system." (PMID 39781525, 2025). "These targets are critically involved in immune dysregulation and the renin–angiotensin system, both of which are central to COVID-19 pathophysiology." (PMID 41471341, 2025). "This study reveals that obesity markedly worsens COVID-19 severity through dysregulation of the renin–angiotensin–aldosterone system (RAAS) and a hyperinflammatory response." (PMID 41562075, 2025). "Evaluation of the Potential Benefit of Renin-angiotensin System Inhibitors (RASi, ACEi/ARB) in High-risk Patients with COVID-19." (PMID 40754875, 2025). "In particular, our analysis newly identified targets such as NOS2, F2, and REN, which are mechanistically relevant to COVID-19 pathogenesis." (PMID 41471341, 2025). "The processes underlying of SARS-CoV-2-induced lung fibrosis are not completely understood, but imbalances of the renin–angiotensin system and low levels of circulating interferon gamma have been reported as potentially relevant to fibrosis following COVID-19." (PMID 38248798, 2024). "The renin-angiotensin system (RAS) has a relevant role in the pathogenesis of COVID-19, as the virus enters host’s cells via the angiotensin-converting enzyme 2 (ACE2)." (PMID 39231898, 2024). "Dysregulation of the renin-angiotensin system is also one of the early mechanisms of lung damage in COVID-19." (PMID 38907196, 2024). "This comparison can highlight key insights, as sarcoidosis shares significant immune similarities with COVID-19, particularly in the renin–angiotensin system (RAS) and immune response pathways." (PMID 39852350, 2024). "As such, it is not surprising that a number of studies have attempted to elucidate the role and balance of the renin–angiotensin system (RAS) in COVID-19." (PMID 38543635, 2024). "COVID-19 incites neuroinflammation, iron dysregulation, reactive oxygen species (ROS) accumulation, antioxidant system repression, renin-angiotensin system (RAS) disruption, and clock gene alteration." (PMID 38641847, 2024). "In COVID-19 and sarcoidosis, the renin–angiotensin system (RAS) and related immune signaling pathways play a vital role in regulating inflammation." (PMID 39852350, 2024). "ACE2 is not only the functional receptor for COVID-19 but also an important endogenous antagonist of the renin-angiotensin system (RAS), which plays a key role in maintaining blood pressure and cardiovascular function." (PMID 39021569, 2024). "Several meta-analyses of clinical trials suggest that both statins and renin–angiotensin–aldosterone system inhibitors (RAASI) have the potential to reduce unfavorable outcomes in patients with COVID-19." (PMID 39518552, 2024). "Estrogen interaction with the renin–angiotensin–aldosterone system, one of the most critical pathways in COVID-19 infectivity, and the modulation of the vasomotor homeostasis are discussed." (PMID 38592095, 2024). "Sarcoidosis shares significant immune similarities with COVID-19, particularly in the renin–angiotensin system (RAS) and immune response pathways." (PMID 39852350, 2024). "The key link between the renin-angiotensin system and COVID-19 is ACE2, which increases the tissue anti-inflammatory response and has been reported to be the primary host-cell receptor for 3 other coronaviruses, namely, HCoV-NL63, SARS-CoV, and SARS-CoV-2." (PMID 37862061, 2023). "Effect modification by adjustment status was observed for HbA1c ≥75 mmol/mol (≥9%), use of statins and use of renin inhibitors with regard to COVID-19-related death and COVID-19 severity." (PMID 37204441, 2023).
COVID-19 (continued). "One consideration is obesity itself having increased ACE2 and dysregulation of the renin-angiotensin-aldosterone system (RAAS) and, in turn, being associated with increased severity of COVID-19." (PMID 41426470, 2023). "Continued receipt of Renin–Angiotensin–Aldosterone inhibitors in patients with COVID-19 has shown potential in producing better clinical outcomes." (PMID 37479767, 2023). "The same study indicated that ACEis or ARRBs have multiple roles in inhibiting inflammation induced by the renin–angiotensin–aldosterone system axis, contributing to their beneficial effects on increasing survival rates in COVID-19 patients." (PMID 37892676, 2023). "Further analyses are needed to elucidate the enigmatic role of the enzymes ACE2 and ACE as well as renin in the RAS system in the context of COVID-19." (PMID 36851710, 2023). "Another study mentioned hypokalemia as an impending expression of COVID-19 as a consequence of the interaction of SARS-CoV-2 with the renin-angiotensin-aldosterone system." (PMID 36860825, 2023). "Previous studies have proposed a possible signal crosstalk between COVID-19 and sarcoidosis, which shared cell signaling pathways such as renin-angiotensin signaling, inhibited autophagy, and induced cell apoptosis." (PMID 38264260, 2023). "Sex differences in cardiovascular disease and COVID-19 share mechanistic foundations, namely, the involvement of both the innate immune system and the canonical renin-angiotensin system (RAS)." (PMID 38077924, 2023). "As proposed at the start of 2020, the SARS-CoV-2 spike protein interacts with the renin-angiotensin system and has a recognized toxicity that was known since before COVID-19 and has been confirmed since." (PMID 37445690, 2023). "Among the different therapeutic agents evaluated for managing COVID-19, the most common that are registered for COVID-19 clinical trials are antivirals, monoclonal antibodies, and drugs modulating the renin–angiotensin system." (PMID 37048652, 2023). "Recent studies directly implicate the cytokine storm in COVID-19 patients with over-expression of AngII in the renin-angiotensin system (RAS)." (PMID 36851526, 2023). "Some anti-hypertensive medications like ACE inhibitors/ARBs impact COVID-19 further than controlling high blood pressure, which goes back to the infection mechanisms relying on the renin–angiotensin system (RAS)." (PMID 38164450, 2023). "In another study, another vascular wall effect of COVID-19 is the increased risk of atherosclerosis secondary to the inflammatory cascade and the alteration of the ACE-2 activity leading to disrupted renin-angiotensin system." (PMID 41541110, 2023). "Sex differences in COVID-19 have a common mechanistic basis, with both the innate immune system and the regulated renin–angiotensin system (RAS) involved." (PMID 38322760, 2023). "Antiplatelet therapy has provided another avenue of great interest to reduce platelet adhesion and aggregation, which is a major consequence of COVID-19 induced renin-angiotension system (RAS) activation." (PMID 36716303, 2023). "Aldosterone levels are increased in COVID-19 patients and the renin–angiotensin–aldosterone system (RAAS) can induce and modulate proinflammatory responses." (PMID 35867189, 2022). "The misregulation of both renin-angiotensin and kinin-kallikrein systems can also explain many liver injuries in COVID-19 patients, such as hepatic vascular resistance and sinusoidal capillarization, portal hypertension, and edema formation." (PMID 36601349, 2022). "This review summarises the literature data and provides an overview of the role and impact of the use of renin–angiotensin–aldosterone system (RAAS) inhibitors in patients with coronavirus disease 2019 (COVID-19) infection." (PMID 35716247, 2022). "The renin-angiotensin system appears to play a central role in the inflammatory response and cardiovascular disease in COVID-19 patients." (PMID 36199292, 2022).
COVID-19 (continued). "The renin-angiotensin system plays an important role in the development and progression of COVID-19 patients." (PMID 36199292, 2022). "Since ACE2 receptors are involved in the pathophysiology of COVID-19, the use of renin–angiotensin–aldosterone system inhibitors for protection against COVID-19-related cardiovascular symptoms remains controversial and debated." (PMID 36135452, 2022). "Interesting, our findings showed that the most popular keywords in cluster#“COVID-19” included “ace2” and “renin-angiotensin-aldosterone system,” suggesting that the associated molecular mechanisms were also of interest." (PMID 36211484, 2022). "Renin-angiotensin-system inhibitors (RASi) were found to have a neutral or protective effect against mortality in COVID-19 adult patients." (PMID 35783862, 2022). "It was reported that a positive relationship exists between renin and sACE2 levels in male and female subjects, and between sACE2 levels and body mass index (BMI) in males, with possible implication for COVID-19." (PMID 36519165, 2022). "Certain BP medications such as renin-angiotensin system blockers are known to be useful in COVID-19." (PMID 36962181, 2022). "Several clinical studies have investigated this possibility, concluding that renin–angiotensin system inhibitors can be safely continued in patients hospitalized with COVID-19." (PMID 35163923, 2022). "Hypopotassemia is also a prevailing electrolyte disorder in COVID-19 patients due to the interaction of SARS-CoV-2 with the renin-angiotensin-aldosterone system." (PMID 36595788, 2022). "It is shown that COVID-19 is activated with renin-angiotensin system imbalance, which activates the classical arm (ACE/Ang II/AT1R) and leads to pulmonary injury, hematological alterations, and hyper-inflammatory state." (PMID 35356739, 2022). "Comorbidities are known to complicate COVID-19 through multiple mechanisms, such as dysfunction of renin–angiotensin, coagulatory, circulatory, and immunological systems." (PMID 35991020, 2022). "The significance of our research is in confirming the role of renin-angiotensin system dysfunction in COVID-19 pathogenesis in a large cohort of patients with diverse disease severity and outcomes." (PMID 35913134, 2022). "SARS-CoV-2 enters in kidney and destroys cells, disrupting the renin–angiotensin–aldosterone system balance, activating coagulation pathways, and damaging the renal vascular endothelium are all effects of the COVID-19." (PMID 36005433, 2022). "Background and Objectives: Vitamin D supplementation plays a key effect in lowering cytokine storms among COVID-19 patients by influencing the activity of the renin-angiotensin system and the production of the angiotensin-2 converting enzyme." (PMID 36295519, 2022). "Since then, numerous studies have been published on the subject, but the exact role of the renin-angiotensin-aldosterone system in the pathogenesis of COVID-19 is still a matter of debate." (PMID 34359922, 2021). "The renin-angiotensin-aldosterone system, a key regulator of vascular homeostasis, effectively participates in COVID-19 CV manifestations." (PMID 34484561, 2021). "Yet some evidence indicated that COVID-19 induced acute lung damage can be reduced by renin-angiotensin-aldosterone system inhibitors and can be beneficial in hypertensive hospitalized COVID-19 patients." (PMID 34220430, 2021). "The results are consistent with previous studies, indicating that the renin-angiotensin system (RAS) plays an important role in the biological mechanisms of COVID-19." (PMID 33919660, 2021). "Our results suggest that interleukin, TLR, TNF, renin-angiotensin, Fc epsilon RI, insulin signaling, PI3K–Akt signaling pathway, and MAPK signaling are partially shared between COVID-19 and its associated comorbidities." (PMID 34067609, 2021).